TRIM27 (tripartite motif containing 27)
Diseases named in the same sentence as TRIM27 in open-access papers (continued):
Sharing a sentence is not in itself a finding about the gene and the disease.
herpesvirus infections (1 paper, 2025). "This interaction promotes TRIM27-mediated ubiquitination of TBK1 and leads to the degradation of TBK1 via the ubiquitin–proteasome pathway, ultimately restricting the innate immune response of microglia to neurotropic herpesvirus infections." (PMID 40285022, 2025).
ischemia (1 paper, 2025). A hypoperfusion of the BLOOD through an organ or tissue caused by a PATHOLOGIC CONSTRICTION or obstruction of its BLOOD VESSELS, or an absence of BLOOD CIRCULATION. "A recent report showed that TRIM27 plays a crucial role in regulating of hepatic ischemia/reperfusion injury by mediating the degradation of TAB2/3 and suppressing downstream TAK1–JNK/p38 signaling." (PMID 40251491, 2025).
lupus (1 paper, 2022). "Tripartite motif-containing 27 (TRIM27), a member of the TRIM protein family, has a strong expression in the LN patients ‘ kidneys, lupus animal models, and human MCs stimulated by LN plasma." (PMID 36591251, 2022).
lymph node metastasis (1 paper, 2020). "Moreover, TRIM27 expression was associated with tumor size and lymph node metastasis, but not other clinical characteristics." (PMID 33264103, 2020).
lymphoma (1 paper, 2019). A malignant (clonal) proliferation of B- lymphocytes or T- lymphocytes which involves the lymph nodes, bone marrow and/or extranodal sites. "TRIM27 also translocates with the RET tyrosine kinase giving higher catalytic activity than RET alone in lymphoma, and resulting in increased cell proliferation and tumorigenesis." (PMID 31342168, 2019).
metastatic tumors (1 paper, 2022). "NCOA4-RET and TRIM27-RET are characteristic gene fusions in salivary Intraductal carcinoma, including invasive and metastatic tumors: is “Intraductal” correct?" (PMID 36227346, 2022).
nasopharyngeal carcinoma (1 paper, 2020). A carcinoma arising from the nasopharyngeal epithelium. "Moreover, the inhibition of TRIM27 expression can inhibit proliferation in ovarian, esophageal, and nasopharyngeal carcinoma cells." (PMID 33173411, 2020).
ovarian serous carcinoma (1 paper, 2017). "RET tyrosine kinase is a fusion partner of TRIM27 (tripartite motif-containing 27), which is highly expressed in normal epithelial cells of the ovary and fallopian tube and in ovarian serous carcinoma cells." (PMID 28871116, 2017).
Papillary Thyroid Carcinomas (1 paper, 2021). "TRIM27 belongs to the RET/PTC (Rearranged in Transformation/Papillary Thyroid Carcinomas) fusion protein subfamily that is involved in oncogenic actions, and the RET proto-oncogene domain of this subfamily is considered essential for its oncogenic potential." (PMID 34284744, 2021).
ulcerative colitis (1 paper, 2026). An inflammatory bowel disease involving the mucosal surface of the large intestine and rectum. "The function of TRIM27 in intestinal epithelial cells (IECs), the mechanism by which TRIM27 inhibits the NF-κB pathway and its dysregulation in ulcerative colitis (UC) remain unclear." (PMID 42017384, 2026).
cancer (35 papers, 2013 to 2025). A tumor composed of atypical neoplastic, often pleomorphic cells that invade other tissues. "High levels of TRIM27 expression in these cancer types are associated with unfavorable clinical features and a poor prognosis." (PMID 38911380, 2024). "The presented evidence demonstrates a consistent association between the TRIM27 expression and the natural progression of cancer." (PMID 38024865, 2023). "TRIM27 is abnormally expressed in many types of cancer, and high TRIM27 expression is associated with worse clinicopathological features and a poor prognosis." (PMID 40395308, 2023). "High TRIM27 expression in these kinds of cancer was associated with worse clinicopathological features and a poor prognosis." (PMID 36200036, 2022). "TRIM27 has been implicated in OC in multiple studies, being higher expressed in cancer samples compared to normal ovarian tissue and higher expressed in cancer cell lines in comparison to untransformed cells." (PMID 34208621, 2021). "We next investigated the roles of TRIM27 in inflammation-associated cancer development by utilizing the AOM/DSS model." (PMID 30143645, 2018). "Studies on the role of TRIM27 in cancer consistently report its carcinogenic effects, aligning with our research." (PMID 39439891, 2024). "An intriguing question to address then, is if the oncogenic potential of TRIM27 can at least partially be due to its role as a promoter of mitophagy, supporting survival and metastasis of cancer cells." (PMID 40395308, 2023). "The aberrant TRIM27 expression in various types of cancer indicates its potential involvement in cancer growth and progression." (PMID 38024865, 2023). "During the past decades, numerous studies showed that TRIM27 was abnormally expressed in many kinds of cancer." (PMID 36200036, 2022). "In various cancers, the oncogenic tripartite motif-containing 27 (TRIM27) protein enhances cell survival, proliferation, migration, and invasion." (PMID 36118880, 2022). "Another study found that TRIM16, TRIM32, TRIM24, TRIM8, TRIM27, TRIM11, and PML are associated with cancer stem cells and the clinical prognosis of RCC, and affect tumor progression." (PMID 36261847, 2022). "The results of our study provide novel evidence that TRIM27 is another example of a TRIM superfamily member that has an oncogenic role in cancer." (PMID 34284744, 2021). "Many downstream signaling pathways of TRIM27 have been identified in cancer, including PTEN/AKT, p38, and STAT3." (PMID 34284744, 2021). "As an oncogene, TRIM27 promotes cancer cell growth in various cancers, including esophageal, lung, and colorectal cancers." (PMID 34284744, 2021). "KIAA0090, ATAD3B, TRIM27 and DMTF1, regulated by hypo-methylated sites, were also associated with cancer." (PMID 33549049, 2021). "TRIM27 expression is elevated in several cancers including colon, lung, endometrial and ovarian, and often correlates with poor prognosis." (PMID 32515734, 2020). "Clinically, lung tissue samples of cancer patients showed increased TRIM27 expression and decreased SIX3 expression." (PMID 33264103, 2020). "An example of this is TRIM27, which exhibits complex function in cancer being characterized as both a tumour suppressor and oncogene." (PMID 31342168, 2019). "Our findings provide important insights to the mechanisms of STAT3 activation induced by the IL-6 family and identify TRIM27 as a potential therapeutic target for treatment of cancer." (PMID 30143645, 2018). "Overexpression of TRIM27 promotes cancer cell growth in vitro and tumor growth in nude mice, whereas knockdown of TRIM27 has opposite effects." (PMID 30143645, 2018).
cancer (continued). "It has been shown that TRIM27 is highly expressed in various cancers including breast, endometrial, ovarian, lung, and colon cancers." (PMID 30143645, 2018). "Change in FEV1 during the 11-year follow-up period was associated with blood DNA methylation level in TRIM27 gene (p value = 1.55 × 10−6), a negative regulator of CD4 T cells, and also involved in cancer development." (PMID 29299071, 2017). "Recently, it has been proposed that down-regulation of PTPMT1 is sufficient to trigger cancer cell death, and TRIM27 participates in regulating cell proliferation in the development of cancer." (PMID 26897165, 2016). "Notably, a previous study showed that TRIM27 promotes glycolysis to drive malignant proliferation in cancer cells." (PMID 40977851, 2025). "TRIM27 expression level is elevated in several types of cancer." (PMID 40395308, 2023). "Next, we focus on the roles of TRIM27 in cancer and other human diseases." (PMID 36200036, 2022). "Meantime, the overexpression of TRIM27 could enhance cellular viability and tumor growth and attenuate the anti-cancer effects of Tamoxifen." (PMID 36200036, 2022). "Here, we systematically review the roles of TRIM27 in cancer and other human diseases." (PMID 36200036, 2022). "Also, the methylation of TRIM27, a negative regulator of CD4 T cells also involved in the development of cancer, was identified to be associated with change in lung function over the 11-year period." (PMID 29299071, 2017). "Hence, we make a review about the roles of TRIM27 in cancer and other human diseases." (PMID 36200036, 2022). "While some TRIM proteins have been associated with cancer, we could find no previous reports relating TRIM27 to EPN tumorigenesis." (PMID 36293188, 2022). "After exclusion criteria were applied, six genes (GBA, ATG10, TRIM27, CD160, ISYNA1, RAD51B) were selected for validating the associations between DNA methylation and BC with MassARRAY EpiTyper assays in validation I (48 sporadic BC cases and 48 matched cancer-free female controls)." (PMID 35812748, 2022). "In addition to its previously identified roles in other cancers, the present study indicates that TRIM27 has oncogenic roles in RCC and could serve as a predictive marker and therapeutic target for a variety types of cancers, including, but not limited to RCC." (PMID 34284744, 2021). "Furthermore, TRIM27 was also described to facilitate migration and invasion of EC cells in vitro through a process that involves at least the decrease of the protein levels of ITGB1, ITGA2 and ITGA5, three integrins implicated in cancer progression." (PMID 34208621, 2021). "TRIM27, which belongs to the superfamily of zinc finger proteins, was previously reported as a transcriptional repressor for suppressing cell senescence, and its high expression could lead to oncogenesis and chemoresistance in multiple types of cancers including OV." (PMID 37270714, 2024). "Our results indicated that higher gene expression levels of RELA were positively correlated with increased IC50 values of cancer therapy drugs, while UBA2, TRIM28, TRIM27, and CAPN3 showed opposite correlations." (PMID 38407971, 2024). "Two of them (TRIM16 and TRIM50) are considered tumor suppressive, while others (TRIM11, TRIM25, TRIM27, TRIM52 and TRIM59) instead promote oncogenesis in this type of cancer." (PMID 34208621, 2021). "Tripartite motif‐containing 27 (TRIM27) belongs to the TRIM protein family, which is closely related to the progression of some certain human cancers." (PMID 31719796, 2019). "This feature is often associated with translocation of TRIM genes and creation of oncogenic fusion products, as in the case of TRIM19/PML, TRIM27/RFP and TRIM24/TIF1α, but they can influence cancer progression also per se." (PMID 30974870, 2019).
cancer (continued). "Interestingly, some other members of the TRIM family are involved in cancer development, some of which are due to chromosomal translocations like TRIM24/TIF1a, TRIM27/RFP, and TRIM33/TIF1g, whose RBCC motifs play a critical role in cell transformation." (PMID 38611029, 2024). "Following, we investigated of the molecular mechanisms responsible for the TRIM27 upregulation in DDP-resistant CRC, and RT-PCR was executed to investigate the mRNA level of TRIM27 in DDP-sensitive and DDP-resistant CRC tissues and across different cancer cell lines." (PMID 38024865, 2023). "TRIM11, TRIM27, TRIM28 and TRIM59 have higher expression in almost all cancers." (PMID 36461099, 2022). "In addition to 4 same genes (KIAA0090, ATAD3B, TRIM27 and DMTF1) with LUSC-C1, ACP1 and SH3YL1 also played important roles in cancer." (PMID 33549049, 2021). "Finally, to our knowledge, there are no cancer studies to date reporting on HILS1, GLMN, TRIM27 and BC069781." (PMID 23135352, 2013). "Whether other proinflammatory cytokines are involved in TRIM27 and Iκbα interactions is not clear at this time; nevertheless, the present study provides further evidence that TRIM superfamily proteins could play either positive or negative roles in NF-κB-induced cancer immunity." (PMID 34284744, 2021).
tumor (23 papers, 2012 to 2025). "For instance, ATP6V0D1 shows significant upregulation in patients with advanced tumor stages, while TRIM27 is notably associated with worse overall survival outcomes." (PMID 39439891, 2024). "High levels TRIM27 were associated with several clinical characteristics, including tumor size, T stage, Fuhrman grade, and metastasis." (PMID 34284744, 2021). "TRIM27 is an oncogene of various tumour types, including colitis‐associated cancer, salivary gland intraductal carcinoma, colon cancer, uterus cancer and prostate cancer." (PMID 33448640, 2020). "Tripartite motif-containing 27 (Trim27) is highly expressed in tumor cells and regulates natural immunity and apoptosis." (PMID 35311628, 2022). "TRIM27 showed a tumor-promoting effect in NIH3T3 mouse embryonic cell lines when the tripartite domain and the tyrosine kinase portion of the RET proto-oncogene become combined through the rearrangement of DNA." (PMID 36313570, 2022). "TRIM27-suppressed tissues exhibited a slower growth rate than the controls, while the tumor weight was reduced in the siTRIM27 group." (PMID 34284744, 2021). "In our study, DNA methylation at cg05293407 in the 200 kb TSS region of TRIM27 upregulated gene expression in tumour tissues, which was consistent with previous reports." (PMID 33448640, 2020). "Here, we profiled DNA methylation of lung adenocarcinoma (LUAD) and lung squamous cell carcinoma (LUSC) tumours from 613 early‐stage NSCLC patients and evaluated associations between CpG methylation of TRIM27 and overall survival." (PMID 33448640, 2020). "We found that overexpression of TRIM27 promoted growth and tumorigenicity of tumor cells in xenograft models." (PMID 30143645, 2018). "Overexpression of TRIM27 markedly promoted anchorage-independent growth of RKO, HEK293, and HeLa cells in vitro and tumor growth in nude mice, whereas knockdown of TRIM27 had opposite effects." (PMID 30143645, 2018). "At present, the research on Trim27 in disease is not fully explored and more efforts are concentrated on the research of tumor and natural immunity against pathogenic microorganisms." (PMID 35311628, 2022). "Finally, we discuss the future directions of TRIM27 research, especially its potential roles in tumor immunity." (PMID 36200036, 2022). "Finally, we provide the future directions of TRIM27 research, especially the discussion about its potential effect in tumor immunity." (PMID 36200036, 2022). "TRIM27 was reported to promote the tumor growth of RCC cell lines in vivo and vitro." (PMID 36200036, 2022). "Overexpression of TRIM27 in tumor tissues promotes tumor progression." (PMID 36313570, 2022). "In fact, TRIM27 is a potent oncogene in various tumor types." (PMID 35371994, 2022). "In addition, we identify the KRAB zinc finger protein, ZNF446, and its associated tripartite motif protein, TRIM27, as obligate components of the ZNF165-SMAD3 complex that also support tumor cell viability." (PMID 32515734, 2020). "We observed a significant decrease in tumor size, suggesting that TRIM27 is essential for TNBC tumor growth in vivo and that inhibition of the ZNF165 transcriptional complex may be a promising avenue of therapeutic intervention." (PMID 32515734, 2020). "Next, we examined whether TRIM27 siRNAs reduce tumor development in vivo." (PMID 34284744, 2021). "The expression of TRIM27 and TRIM47 was remarkably higher in KIRC tumor compared to that in normal tissues, and their increased expression was associated with worse OS, indicating an oncogenic role in KIRC." (PMID 35371994, 2022). "We next perturbed TRIM27 as a means to inhibit the activity of the ZNF165 transcriptional complex and assess its impact on TNBC tumor growth and survival at the orthotopic site in mice." (PMID 32515734, 2020).
tumor (continued). "Because OC is primarily a tumor of epithelial origin, the expression of TRIM proteins was analyzed in epithelial cells, and the eight most highly expressed genes (TRIM28, TRIM27, TRIM33, TRIM38, TRIM47, TRIM56, TRIM8, and TRIM24) were determined." (PMID 38881325, 2024). "Furthermore, some other TRIMs have been reported to be engaged in tumor cell proliferation; for example, SIX3 is ubiquitinated and degraded by TRIM27, and TRIM27-SIX3 signaling induces cell proliferation and metastasis in NSCLC." (PMID 36249749, 2022). "TRIM27 is essential for ZNF165 transcriptional activity and tumor growth in vivo." (PMID 32515734, 2020). "(H) Tumor volumes from mice orthotopically injected with SUM159T-Luciferase cells stably expressing shRNAs against TRIM27 (n = 10) or a non-targeting control (n = 9)." (PMID 32515734, 2020). "Importantly, we find that TRIM27 alone is necessary for ZNF165 transcriptional activity and is required for TNBC tumor growth in vivo using an orthotopic xenograft model in immunocompromised mice." (PMID 32515734, 2020). "Expression of TRIM27 and HLA-DQA1 was analyzed with the stratification of different sex, age, family history, high/low-incidence areas, the regional lymph node metastasis and tumor location." (PMID 24595008, 2014). "In the absence of extracellular matrix, TRIM27 depletion dramatically reduced tumor cell growth." (PMID 32515734, 2020).